ZNF302 (zinc finger protein 302)
Description:
May be involved in transcriptional regulation.
Synonyms: ZNF135L; ZNF140L; ZNF327; HSD16; MST154; MSTP154
Tractability: PROTAC: UniProt records ubiquitination sites on it; ubiquitination databases record sites on it.
Gene: Protein-coding gene on chromosome 19 (34,677,084 to 34,687,065, forward strand). Ensembl gene ENSG00000089335.
Subcellular location: Nucleus
Subcellular location (Human Protein Atlas): Nucleoplasm
Pathways (Reactome):
Gene expression (Transcription): Generic Transcription Pathway
Gene Ontology:
Molecular function: protein binding; DNA-binding transcription factor activity, RNA polymerase II-specific; RNA polymerase II cis-regulatory region sequence-specific DNA binding
Biological process: regulation of transcription by RNA polymerase II; regulation of DNA-templated transcription
Cellular component: nucleus
Genetic constraint (gnomAD): Loss-of-function variants: 12 observed, 10.53 expected, observed/expected ratio (o/e) 1.14, 90% interval 0.73 to 1.76. The upper end of that interval is the gene's LOEUF score, 1.76, which puts it in group 6 of 6, group 1 being the genes least tolerant of losing a copy. Missense variants: 461 observed, 481.75 expected, observed/expected ratio (o/e) 0.96, 90% interval 0.89 to 1.03. Synonymous variants: 178 observed, 162.28 expected, observed/expected ratio (o/e) 1.1, 90% interval 0.97 to 1.24.
Homologues: Orthologues: chimpanzee ZNF302 (95% identical), zebrafish znf646 (23% identical), zebrafish si:dkey-89b17.4 (22% identical), Drosophila melanogaster CG18011 (21% identical), zebrafish znf576.1 (19% identical), zebrafish zgc:66472 (16% identical), Drosophila melanogaster az2 (16% identical), Drosophila melanogaster CG1602 (15% identical), Caenorhabditis elegans ztf-15 (15% identical), Drosophila melanogaster CG2129 (15% identical), Drosophila melanogaster mld (14% identical), Drosophila melanogaster CG30020 (14% identical), and 6 more. Paralogues in human: ZNF181 (90% identical), ZNF184 (47% identical), ZNF84 (47% identical), ZNF347 (46% identical), ZNF160 (45% identical), ZNF208 (45% identical), ZNF91 (45% identical), ZNF107 (45% identical), ZNF569 (45% identical), ZNF99 (44% identical), ZNF420 (42% identical), ZNF729 (41% identical), and 24 more.
Diseases named in the same sentence as ZNF302 in open-access papers:
ZNF302 is named in the same sentence as 6 diseases in open-access papers, as found by Europe PMC text mining. Sharing a sentence is not in itself a finding about the gene and the disease. The quoted sentences say what the papers report.
breast carcinoma (1 paper, 2023). "We obtained ChIP-seq data of the candidate transcription factors FOSB (ENCSR569XNP), ZNF302 (ENCFF037UPH), SP1 (ENCFF072FPF), ELK1 (ENCFF123KER), and FOXF2 (ENCFF008ABX) in a breast cancer cell line MCF-7 from ENCODE." (PMID 37173692, 2023).
endometrial carcinoma (1 paper, 2021). A malignant tumor arising from the epithelium that lines the cavity of the uterine body. "Similarly, ZNF302 is predicted to be a miR-1260b target gene (score = 98), and high expression of ZNF302 is associated with poor survival in Endometrial Carcinoma in TCGA-UCEC." (PMID 34805186, 2021).
myocardial infarction (1 paper, 2024). Gross necrosis of the myocardium, as a result of interruption of the blood supply to the area, as in coronary thrombosis. "The expressions of CBLB and ZNF302 in serum collected at 48 h and 1 week post-myocardial infarction were significantly higher compared to the sham operation group." (PMID 38827298, 2024). "The serum of mice was collected at three different time points for analysis, revealing an increase in the expression of CBLB and ZNF302 at 3 h post-myocardial infarction." (PMID 38827298, 2024).
cardiovascular disease (1 paper, 2024). "Therefore, ZNF302 plays a key role in the progression of cardiac development, suggesting that ZNF302 may be a potential diagnostic factor for cardiovascular disease." (PMID 38827298, 2024).
ZNF302 also shares sentences with these, for which no sentence is quoted: cancer (1 paper); tumor (1).